MIR4453HG (MIR4453 host gene)
Synonyms: DKFZP434I0714; LINC02486
Gene: Long non-coding RNA gene on chromosome 4 (152,536,260 to 152,539,263, forward strand). Ensembl gene ENSG00000268471.
Diseases named in the same sentence as MIR4453HG in open-access papers:
MIR4453HG is named in the same sentence as 1 disease in open-access papers, as found by Europe PMC text mining. Sharing a sentence is not in itself a finding about the gene and the disease. The quoted sentences say what the papers report.
glioma (1 paper, 2019). A benign or malignant brain and spinal cord tumor that arises from glial cells (astrocytes, oligodendrocytes, ependymal cells). "Subsequently, 10 autophagy‐associated lncRNAs with prognostic value (PCBP1‐AS1, TP53TG1, DHRS4‐AS1, ZNF674‐AS1, GABPB1‐AS1, DDX11‐AS1, SBF2‐AS1, MIR4453HG, MAPKAPK5‐AS1 and COX10‐AS1) were identified in glioma patients using multivariate Cox regression analyses." (PMID 30984540, 2019).